GDF11 (growth differentiation factor 11)
Description:
Secreted signal that acts globally to regulate anterior/posterior axial patterning during development. May play critical roles in patterning both mesodermal and neural tissues (By similarity). It is required for proper vertebral patterning and orofacial development. Signals through activin receptors type-2, ACVR2A and ACVR2B, and activin receptors type-1, ACVR1B, ACVR1C and TGFBR1 leading to the phosphorylation of SMAD2 and SMAD3.
Synonyms: BMP-11; BMP11; VHO
Tractability: Antibody: UniProt places it where antibodies can reach, with high confidence; UniProt predicts a signal peptide or a membrane-spanning region; its Gene Ontology location is reachable by antibodies, with medium confidence.
Gene: Protein-coding gene on chromosome 12 (55,743,122 to 55,757,264, forward strand). Ensembl gene ENSG00000135414.
Subcellular location: Secreted
Subcellular location (Human Protein Atlas): Vesicles; Golgi apparatus; Predicted to be secreted
Gene Ontology:
Molecular function: protein binding; cytokine activity; growth factor activity; signaling receptor binding
Biological process: activin receptor signaling pathway; positive regulation of SMAD protein signal transduction; mesoderm development; nervous system development; skeletal system development; transforming growth factor beta receptor signaling pathway; negative regulation of neuron differentiation
Cellular component: protein-containing complex; extracellular region
Genetic constraint (gnomAD): Loss-of-function variants: 12 observed, 31.66 expected, observed/expected ratio (o/e) 0.38, 90% interval 0.24 to 0.61. The upper end of that interval is the gene's LOEUF score, 0.61, which puts it in group 2 of 6, group 1 being the genes least tolerant of losing a copy. Missense variants: 338 observed, 507.53 expected, observed/expected ratio (o/e) 0.67, 90% interval 0.61 to 0.73. Synonymous variants: 208 observed, 210.54 expected, observed/expected ratio (o/e) 0.99, 90% interval 0.88 to 1.11.
Homologues: Orthologues: chimpanzee GDF11 (100% identical), macaque GDF11 (100% identical), rat Gdf11 (99% identical), dog GDF11 (99% identical), mouse Gdf11 (99% identical), pig GDF11 (98% identical), rabbit GDF11 (93% identical), tropical clawed frog gdf11 (75% identical), guinea pig GDF11 (64% identical). Paralogues in human: MSTN (57% identical), BMP6 (24% identical), TGFB3 (24% identical), TGFB2 (23% identical), BMP7 (22% identical), BMP5 (22% identical), BMP10 (21% identical), INHBB (21% identical), INHBC (21% identical), GDF2 (21% identical), BMP2 (21% identical), TGFB1 (21% identical), and 19 more.
Diseases named in the same sentence as GDF11 in open-access papers:
GDF11 is named in the same sentence as 142 diseases in open-access papers, as found by Europe PMC text mining. Sharing a sentence is not in itself a finding about the gene and the disease. The quoted sentences say what the papers report.
cardiac hypertrophy (32 papers, 2016 to 2025). "Growth differentiation factor 11 (GDF11) is a member of the TGF-β protein family that has been implicated in the development of cardiac hypertrophy." (PMID 34510201, 2021). "GDF11 supplementation reversed cardiac hypertrophy, bone loss, and pulmonary dysfunction in old mice, suggesting that GDF11 has a rejuvenating effect." (PMID 32365331, 2020). "Earlier studies have demonstrated that serum, spleen and kidney levels of GDF11/8 decline with age and restoration of GDF11 reverses age-associated cardiac hypertrophy, skeletal muscle dysfunction, hippocampal vascularity and increases neural stem-cell proliferation." (PMID 32365331, 2020). "As noted, ARNI is recommended for HFrEF, while GDF11 and EVs synergistically improve ventricular systolic function via anti-myocardial hypertrophy and inhibiting myocardial fibrosis, respectively." (PMID 40969375, 2025). "Growth differentiation factor 11 (GDF11) is a member of the transforming growth factor β superfamily, which regulates oxidative stress, inflammation, and cell survival to mitigate myocardial hypertrophy, myocardial infarction, and vascular injury." (PMID 38715043, 2024). "According to the study, systemic GDF11 levels decreased with age, and treating old mice with recombinant GDF11 reversed histopathological and molecular markers of cardiac hypertrophy." (PMID 39237910, 2024). "An initial report showed that administration of exogenous GDF11 at 0.1 mg/kg to aged mice reduced cardiac hypertrophy, like the heterochronic parabiosis experiments." (PMID 38235060, 2023). "Previous studies have shown that administration of exogenous recombinant GDF11 to aged mice reduces cardiac hypertrophy, and fetal cardiac GDF8 has also been implicated in early-stage heart development." (PMID 36631218, 2023). "The Houser lab then showed, in 2016, with careful dose-response experiments that exogenous administration of GDF11 significantly reduced TAC-induced cardiac hypertrophy and improved cardiac function in a dose-dependent fashion." (PMID 38235060, 2023). "The potential benefits of GDF11 in cardiac hypertrophy have now been confirmed by multiple laboratories." (PMID 38235060, 2023). "This study was conducted to precisely resolve the relationships among GDF11, myostatin, and cardiac hypertrophy, while simultaneously comparing their genetic architectures to uncover any mechanisms that link them." (PMID 34510201, 2021). "Circulating GDF11 levels were found to decrease during aging, and restoring GDF11 in aged mice improved histopathological indicators of cardiac hypertrophy, recapitulating the effect of young blood." (PMID 34510201, 2021). "This study was conducted to resolve the statistical and genetic relationships among GDF11, myostatin, and cardiac hypertrophy in a mouse model of human genetics, the Diversity Outbred (DO) stock." (PMID 34510201, 2021). "Growth differentiation factor 11 (GDF11) is a member of the transforming growth factor β superfamily that alleviates cardiac hypertrophy, myocardial infarction, and vascular injury by regulating oxidative stress, inflammation, and cell survival." (PMID 34262905, 2021). "Among these candidates, GDF11 level declined with age and administration of GDF11 reversed age-related cardiac hypertrophy in old mice." (PMID 33197235, 2020). "Initial studies suggesting a rejuvenating action for GDF11 showed that after parabiosis experiments in mice, reversal of age-related cardiac hypertrophy was due to a blood-borne factor that was attributed to GDF11." (PMID 31248139, 2019). "Recently, the goal of a study in old mice was to reexamine the possibility to restore youthful levels of GDF11 by injecting rGDF11 and thus reversing cardiac hypertrophy and imparting a young phenotype to the old heart." (PMID 30545044, 2018). "Growth differentiation factor 11 (GDF11), a member of the transforming growth factor-β family, has been shown to act as a negative regulator in cardiac hypertrophy." (PMID 29783655, 2018).
cardiac hypertrophy (continued). "Recent studies reported that GDF11 was a rejuvenation factor that reversed age-related heart hypertrophy and improved brain capillary and muscle function." (PMID 29113418, 2017). "Though myostatin has an established, anti-hypertrophic effect on muscle, including a direct regulatory effect on cardiomyocytes, it still remains unclear whether GDF11 has the same, or distinct, effects on cardiac hypertrophy." (PMID 34510201, 2021). "In addition, exogenous administration of GDF11 blocks cardiac hypertrophy induced by various stimuli or prohypertrophic conditions." (PMID 29783655, 2018). "Cardiomyocyte growth is finely controlled by Ca2+-mediated signaling; however, it is still unclear whether the actions of GDF11 involve Ca2+-mediated pathways to induce negative regulation during cardiac hypertrophy." (PMID 29783655, 2018). "An endogenous compound called growth differentiation factor 11 (GDF11) is a circulating negative regulator of cardiac hypertrophy, suggesting that raising GDF11 levels could potentially treat or prevent cardiac diseases." (PMID 30545044, 2018). "For example, it was found that GDF11 in the blood promotes nerve regeneration using the technique of heterochronic parabiosis, improves skeletal muscle function, and reverses ventricular hypertrophy in the aged mice, highlighting GDF11 as a promising rejuvenating factor." (PMID 34588995, 2021). "Overall, we discovered unique relationships among GDF11, myostatin, and indicators of cardiac hypertrophy, as well as distinct loci and candidate genes behind each phenotype, and our results point to molecular pathways that will be interrogated in future studies of GDF11 and the heart." (PMID 34510201, 2021). "However, recent evidence suggests that GDF11 is an important circulating factor that declines with age and exogenous treatment with GDF11 can reverse age-related effects including reducing cardiac hypertrophy, improving skeletal muscle regeneration, and promoting neurogenesis." (PMID 28257634, 2017). "The results that GDF11 administration may reverse cardiac hypertrophy have also been questioned." (PMID 28580190, 2017). "Indeed, several reports have emerged in response to these data, indicating non‐specific GDF11 detection methods, irreproducibility of GDF11 decline with age, prevention of cardiac hypertrophy, and the enhancement of muscle regeneration." (PMID 28270449, 2017). "Nevertheless, interest persists from pharmaceutical and biotechnology companies in the potential effects of GDF11 in age-related organ dysfunction, and several studies support the notion that exogenous GDF11 may regulate cardiac hypertrophy and skeletal muscle repair in older animals." (PMID 36631218, 2023). "Historically, GDF-11 was described in studies using the heterochronic parabiosis model, where GDF-11 was shown to reverse aging-related cardiac hypertrophy." (PMID 34336096, 2021). "Administration of recombinant GDF11 to aged mice can restore subventricular zone (SVZ) vascularization, enhance neurogenesis, and reverse age-related dysfunction in skeletal muscle and cardiac hypertrophy." (PMID 32513253, 2020). "Conversely, other reports have indicated that GDF11 does not prevent cardiac hypertrophy in a pressure overload model, and that GDF11 circulating levels increase with age and induce cardiac hypertrophy, as well as inhibiting skeletal muscle regeneration." (PMID 29783655, 2018). "Interestingly, a recent study showed cardiomyocyte-specific depletion of GDF11 (Myh6-Cre; Gdf11 floxed mice) did not result in cardiac hypertrophy but showed left ventricular dilatation." (PMID 35012677, 2022).
Stroke (14 papers, 2018 to 2025). Sudden impairment of blood flow to a part of the brain due to occlusion or rupture of an artery to the brain. "Five days of GDF11 administration to old male mice initiated five days after stroke reduced brain tissue loss, mortality and improved sensorimotor outcomes at 30 days." (PMID 32365331, 2020). "Given that age increases susceptibility to stroke, we hypothesized that GDF-11 may be directly protective to neurons following ischemia." (PMID 33013673, 2020). "It is unknown if the age-related loss of GDF11 contributes to the poor post-stroke repair seen in aged animals." (PMID 32365331, 2020). "We show that GDF11 treatment is protective in the older stroke mice and significantly reduced mortality, but the underlying mechanisms could be manifold." (PMID 32365331, 2020). "GDF11 promotes the expression of Smad3, which inhibits cell apoptosis and reduces brain injury after stroke by activating the TGF-β/Smad3 signaling pathway." (PMID 38203348, 2023). "CircUCK2 can activate the TGF-β/Smad3 signaling pathway through the miR-125b-5p/GDF11 axis in order to reduce cell apoptosis and improve neuronal injury after stroke." (PMID 38203348, 2023). "Following a stroke, the brain releases ischemic signals, the activated spleen released its GDF11 reserves into the blood circulation, allowing it to deposit in the damaged brain." (PMID 35250458, 2022). "The effects of taVNS on post-stroke recovery, as well as up-regulation of cerebral GDF11, and down-regulation of splenic GDF11, indicate brain-spleen communication." (PMID 35250458, 2022). "Five days after MCAo, mice received and bromodeoxyuridine / 5-Bromo-2'-deoxyuridine (BrdU) and either recombinant GDF11 or vehicle for five days and were assessed for recovery for one month following stroke." (PMID 32365331, 2020). "Less is known about the potential of GDF11 to improve recovery after an acute injury, such as stroke, in aged mice." (PMID 32365331, 2020). "As GDF11 signaling decreases with age and stroke is primarily a disease of the elderly, examining its effects in aged models of stroke increases translational relevance." (PMID 32365331, 2020). "Under in vivo stroke conditions, GDF-11 has been shown to reduce infarct volume and improve behavioral outcomes mainly due to both angiogenesis and endothelial cell proliferation." (PMID 33013673, 2020). "Secondly, although we show rGDF11 administration in the recovery phase is beneficial, additional studies testing how GDF11 modulates gliosis and blood-brain barrier recovery after stroke are needed, as are studies examining both sexes." (PMID 32365331, 2020). "To determine if GDF11 altered early neurological outcomes in aged male animals after stroke, we administered recombinant growth differentiation factor-11 (rGDF11) five days after middle cerebral artery occlusion (MCAo) for 5 days." (PMID 32365331, 2020). "Mice in the rGDF11 group were more mobile during the tail suspension task compared to the stroke vehicle group suggesting a role of GDF11 in depressive behavior." (PMID 32365331, 2020). "Thirty days post-MCAo, the number of NeuN+ cells and intensity was higher in the MCAo rGDF11 group as compared to MCAo vehicle (p<0.05) suggesting a protective role of GDF11 during stroke recovery." (PMID 32365331, 2020). "At day 10 post-stroke, a significant decrease (p<0.05) in the neurological deficit score was seen in the GDF11 treated mice suggesting an earlier recovery of neurological deficits." (PMID 32365331, 2020). "We observed a restoration of MBP and synaptophysin levels in the MCAo GDF11 group in the peri-infarct area and CC at 30 days after stroke." (PMID 32365331, 2020). "We found that delayed treatment with recombinant GDF11 (rGDF11) at 7 days after stroke promoted neurogenesis and angiogenesis and improved behavioral outcome by regulating the TGF-β/Smad2/3 signaling pathway." (PMID 30061815, 2018).
Stroke (continued). "In this study, we explored the effects of GDF11 on brain repair during the recovery phase after stroke." (PMID 30061815, 2018). "Our aim was to investigate the effects of GDF11 on brain repair during the recovery phase after stroke." (PMID 30061815, 2018). "In this study, we investigated the role of GDF11 on stroke recovery in a mouse model of distal occlusion of middle cerebral artery." (PMID 30061815, 2018). "Here we found that the ipsilateral peri-infarct cortex and SVZ level of GDF11 increased after stroke." (PMID 30061815, 2018). "However, many studies have now confirmed that exogenous administration of GDF11 can improve physiology in disease models, including cardiac fibrosis, experimental stroke, and disordered metabolism." (PMID 38235060, 2023). "We observed an increase in CD31 with GDF11 treatment in older stroke animals." (PMID 32365331, 2020). "However further studies are needed to validate the role of GDF11 on the repair and recovery mechanisms in stroke injury." (PMID 32365331, 2020). "Furthermore, an increase (p<0.05) in BrdU/lectin+ cells was observed in the GDF11 group as compared to the vehicle group at day 30 post-stroke, reflecting an increase in angiogenesis." (PMID 32365331, 2020). "Treatment with GDF-11 can effectively improve the symptoms of Alzheimer's and stroke patients." (PMID 33364986, 2020). "The effects of exogenous GDF11 given during stroke recovery in aged animals were also examined." (PMID 32365331, 2020). "GDF11 supplementation reduced mortality and improved sensorimotor deficits after stroke." (PMID 32365331, 2020). "A decrease in brain IL-15 and IL-18 levels at day 10 along with reduced gliosis at day 30-post stroke could partially explain the protective role of GDF11." (PMID 32365331, 2020). "Consistent with its pro-neurogenic and pro-angiogenic properties in the adult brain, GDF11 treatment may improve stroke condition." (PMID 31330871, 2019). "A number of experimental and clinical studies investigated the role of GDF11 on stroke recovery." (PMID 31330871, 2019). "It should be noted that the level of GDF11 may be a predictive biomarker of heart attack, stroke, congestive heart failure, and overall mortality in patients." (PMID 30061815, 2018). "Therefore, limiting the amount of neuronal exposure to GDF-11 during a stroke could restrict its neurotoxic effects while maintaining their vasculoprotective effects to help improve recovery of the brain." (PMID 33013673, 2020). "Furthermore, GDF11 treatment improved white matter integrity post-stroke." (PMID 32365331, 2020). "Our study suggest that GDF11 is a key regulator of neurovascular regeneration after stroke and this result may provide a potential therapeutic treatment for improving the functional outcome after stroke." (PMID 30061815, 2018). "Growth differentiation factor 11 (GRF11) is another rejuvenating factor, and its recombinant form is in clinical development for improving stroke-recovery and acute inflammatory conditions, including pancreatitis." (PMID 39953524, 2025). "Hence, these findings suggest that GDF11 may have an anti-inflammatory role after stroke." (PMID 32365331, 2020). "We found that GDF11 was upregulated in the ipsilateral SVZ and the peri-infarct cortex at 14 days after stroke." (PMID 30061815, 2018). "Lack of GDF11 specific inhibitors and GDF11 knockout animals limit our understanding of the neuroprotective mechanism of GDF11 in aging and stroke." (PMID 32365331, 2020). "Western blot analysis showed that GDF11 was significantly upregulated in the ipsilateral peri-infarct cortex and SVZ compared to the contralateral hemisphere and the sham-operated mice at 14 days after stroke." (PMID 30061815, 2018).
Stroke (continued). "Although we did observe an increase in BrdU+ cells in the rGDF11 treated mice, it is possible that the shorter duration or dose of GDF11 used in our study was not sufficient to stimulate the formation of new neurons in stroke animals or that the administration of BrdU was timed incorrectly." (PMID 32365331, 2020).